GLI1 (GLI family zinc finger 1)
Diseases named in the same sentence as GLI1 in open-access papers (continued):
Sharing a sentence is not in itself a finding about the gene and the disease.
glioma (continued). "For example, in glioma cells, GLI1 induces non-canonical temozolomide resistance and its knockdown or treatment with aspirin re-sensitizes the cells to the drug." (PMID 30158435, 2018). "Finally, we demonstrate that combined Hh/GLI1 inhibition and TMZ treatment induces apoptosis and suppresses the growth of U87-MG cells cultured as neurospheres, suggesting an abrogation of glioma stem cell-like behavior." (PMID 29930746, 2018). "GLI1 knockdown reduced SPP1 mRNA and protein levels in glioma cells." (PMID 28030801, 2017). "Up-regulated SPP1 expression is associated with binding of the GLI1 transcription factor to the promoter and OCT4 (octamer-binding transcription factor 4) to the first SPP1 intron of the SPP1 gene in human glioma cells but not in non-transformed astrocytes." (PMID 28030801, 2017). "In conclusion, our studies revealed that aspirin could inhibit glioma cells proliferation, induce apoptosis through SHH/GLI1 signaling pathway and aspirin potentially attenuate intrinsic and non-canonical TMZ resistance." (PMID 28446712, 2017). "The main findings of this study are: i) SPP1 overexpression in glioma initiating cells, ii) a novel mechanism of transcriptional regulation of the SPP1 by GLI1 and OCT4, and iii) demonstration of the supportive role of tumour-derived osteopontin/SPP1 in self-renewal of glioma initiating cells." (PMID 28030801, 2017). "Furthermore glial tumor markers such as OLIG2 and GLI1 and GSC markers such as MSI1 and SOX2 were also significantly reduced in F3.EGFRviii spheres." (PMID 28830458, 2017). "The Gli1 transcription factor is one of the SONIC Hedgehog (SHH) pathway target genes, and it was found that HH-Gli signaling was essential for the maintenance of cancer stem-like cells in human gastric cancers and gliomas." (PMID 26769843, 2016). "In addition, the blockade of Shh/GLI1 and IGF pathways sensitizes glioma stem cells to the chemotherapeutic agent temozolomide." (PMID 24550888, 2014). "Therefore, in order to suppress the GLI activation in cytoplasm, we directly blocked the activity of GLI1 and GLI2 in cytoplasm and also SMO in membrane of the Glioma scenario (GS) by putting ‘0’ or “OFF” as their logical states." (PMID 23935937, 2013). "In case of Glioma, the total numbers of activators on GLI1 and GLI2 proteins were 16 and 6, whereas in case of normal scenario there were 11 and 5 proteins activating the expression of GLI1 and GLI2 proteins, respectively." (PMID 23935937, 2013). "However, cyclopamine does not suppress BMI1 mRNA levels, Gli1 overexpression only marginally increases BMI1 mRNA levels in Daoy glioma spheres." (PMID 33499351, 2021). "GLI1 activity in GBM is also regulated through crosstalk with other pathways including Ras, Myc, and Akt, which may contribute to resistance to SHH inhibitors in gliomas." (PMID 32957513, 2020). "In sum, through Gli1 down-regulation, MCyp yielded better performance than Cyp solution in inhibiting cell proliferation, CSC and cell invasion, which could reduce the escape of glioma cells from chemotherapy." (PMID 28477008, 2017). "The results displayed that GLI1 dependence manner for DNA damage repair activity could mediate non-canonical TMZ-resistance in glioma cells." (PMID 28446712, 2017). "In another study, GLI1-3 expression, along with its target genes, FOXM1 and BMI1, were present in all the tested glioma cell lines in contrast to normal brain tissue that lacked GLI1 expression." (PMID 35409080, 2022). "We demonstrated binding of GLI1 to the proximal promoter of SPP1 gene by chromatin immunoprecipitation (ChIP) assay in three human glioma cell lines, including primary human WG4 glioma cultures, but not in NHA." (PMID 28030801, 2017). "Collectively, data demonstrated that aspirin repressed the GLI1 activation following TMZ treatment in the combined group, which overcame non-canonical TMZ-resistance in glioma cells." (PMID 28446712, 2017).
glioma (continued). "We demonstrated that transcription factors OCT4 and GLI1, involved in maintenance of the stemness phenotype in embryonic and cancer stem cells, bind to the SPP1 gene in glioma cells, but not in normal astrocytes." (PMID 28030801, 2017). "Moreover, some studies demonstrated GLI1 inhibition induced almost all DNA damage in human cancer, which suggested acquired overexpression GLI1 could induce non-canonical TMZ-resistance in glioma cells." (PMID 28446712, 2017).
melanoma (84 papers, 2010 to 2026). A malignant, usually aggressive tumor composed of atypical, neoplastic melanocytes. "For example, pancreatic-derived CAFs show elevated levels of SMO and GLI1 expression, whilst melanoma-associated CAFs exhibit reduced extracellular matrix production and paracrine signalling when β-catenin is inhibited." (PMID 35159339, 2022). "HES1, a downstream target of Notch, binds and represses GLI1 (glioma-associated oncogene 1) and regulates Hh signaling in melanoma cell lines and primary glioblastoma cultures." (PMID 33430387, 2021). "Here, oncogenic RAS variants, and constitutively active MEK1 or AKT1, caused nuclear localization of myc-tagged GLI1 in the human melanoma cell line SK-Mel2." (PMID 33081032, 2020). "Missense and nonsense mutations of GLI1 were also documented in melanoma and squamous cell carcinoma." (PMID 26633513, 2015). "To address the possible role of endogenous, physiological oncogenic GLI activity, we performed RNA-interference (RNAi)-mediated GLI1 inactivation in human BRAFV600E mutated melanoma cells (WM35) and treated the cells with IL6 [75 ng/mL] for 18 h to activate IDO1 expression via STAT3." (PMID 39962447, 2025). "However, the impact of the transcription factor GLI1 on tumor-associated immune cells is still unexplored in melanoma." (PMID 39090759, 2024). "Similarly, the induction of vemurafenib resistance in melanoma cell lines was associated with frequent elevated expression of GLI1, while expression of GLI2 was elevated but to a lesser extent." (PMID 34572373, 2021). "Studies in melanoma and hepatocellular carcinoma have linked Gli1 to vascular/capsular invasion, advanced tumor stage, and upregulation of matrix metalloprotease (MMP)-2 and MMP-9, while siRNA silencing of Gli1 successfully reduced invasion and increased E-cadherin expression." (PMID 29416661, 2018). "In this study, using quantitative real-time PCR and cDNA microarray analysis, we show that the GLI1 is expressed in human melanoma cell lines and its expression is significantly higher in primary human melanoma tissues harboring BRAFV600E mutation as compared to those with wild type BRAF." (PMID 23935925, 2013). "Consistent with our findings, Gunarta and collaborators reported that suppression of GLI1 decreases the invasive capacity of melanoma cells." (PMID 41596411, 2026). "Using two different shRNA constructs, we performed RNAi-mediated knockdown of GLI1 in the BRAFV600E mutant human melanoma cell line WM35 treated for 18 h with IFNγ [10 ng/mL]." (PMID 39962447, 2025). "Genetic and pharmacologic inhibition of ERK5 reduced the transcriptional activity of ectopic GLI1 in melanoma cells." (PMID 39998753, 2025). "This inhibition of SMO and Gli1 by Itraconazole not only reduces melanoma cell proliferation but also induces apoptosis." (PMID 39917616, 2025). "In human melanoma cells, inhibition of GLI1 expression prevented the induction of IDO1 expression in response to IL6/STAT3 and IFNγ/STAT1 signaling." (PMID 39962447, 2025). "Due to S100 immunoreactivity, tumors such as melanoma with epithelioid morphologies should be considered in the differential diagnosis of GLI1-rearranged enteric tumors." (PMID 39851545, 2025). "Like IL6/STAT3, genetic and pharmacological targeting of GLI1 showed that IFNγ/STAT1 requires functional GLI as a second signal for the full-blown induction of IDO1 in human melanoma cells." (PMID 39962447, 2025). "In our study, Shh and Gli1 underwent downregulation in A375 and A2058 cells receiving itraconazole treatment, proving the possible role of itraconazole in restraining melanoma growth via inhibiting Hh pathway." (PMID 39917616, 2025). "In line with our observations of IL6-treated cells, genetic inhibition of GLI1 expression strongly reduced IFNγ-mediated transcriptional induction of IDO1 in WM35 melanoma cells as measured by qPCR." (PMID 39962447, 2025).
melanoma (continued). "Altogether, these data suggest that the depletion of GLI1 in melanoma cells promotes moDC recruitment and activation." (PMID 39090759, 2024). "Overexpression of GLI1 in A375 melanoma cells drastically downregulated CCL7, CCL2, CCL20 and CXCL8 mRNA level." (PMID 39090759, 2024). "Knockdown of Gli1 and Gli2 was found to restore drug sensitivity in vemurafenib-resistant melanoma cells." (PMID 39199632, 2024). "Pietrobono and coworkers demonstrated that, in melanoma cells, these compounds specifically target the Smo protein, thus leading to a decreased expression of Gli1, and significantly impair the self-renewal of the CSC subpopulation." (PMID 39199632, 2024). "Cytokine array from SSM2c cells transduced with LV-c or LV-shGLI1 showed a significantly higher secretion of CCL7, CCL2, CCL20 and CXCL8 (IL-8) in CM collected from GLI1-silenced melanoma cells." (PMID 39090759, 2024). "We show that melanoma cell-intrinsic GLI1 alters the infiltration of immune cells by increasing PMN-MDSCs and decreasing dendritic cells (DCs) in vivo." (PMID 39090759, 2024). "led to the development of novel SMO inhibitors based on acylguanidine or acylthiourea scaffolds, which specifically target SMO in melanoma cells, thereby reducing Gli1 expression, inducing DNA damage and apoptosis, and inhibiting the self-renewal of MSCs." (PMID 39611156, 2024). "The immune-modulatory activity of GLI1 was evaluated in a syngeneic B16F10 melanoma mouse model assessing immune populations by flow cytometry." (PMID 39090759, 2024). "Conditioned media (CM) from GLI1-overexpressing mouse melanoma cells was used to culture PMN-MDSCs, and the effects of CM were evaluated by Transwell invasion assay and T cell inhibition." (PMID 39090759, 2024). "This phosphorylation prevents GSK3β from binding to GLI1 and β-catenin, leading to the inhibition of degradation and the increased expression of GLI1 and β-catenin in melanoma." (PMID 39452835, 2024). "Our findings show that expression of GLI1 in melanoma cells not only sustains the expansion and recruitment of pro-tumorigenic PMN-MDSCs and skews them towards an immunosuppressive phenotype, but also diminishes anti-tumorigenic cDC populations." (PMID 39090759, 2024). "GLI1 overexpression in human melanoma A375 cells, which express low level of GLI1, increased CX3CL1 mRNA expression, suggesting a direct transcriptional regulation of CX3CL1 by GLI1." (PMID 39090759, 2024). "The degree of GLI1 overexpression using the pBABE vector is biologically feasible in melanoma cells." (PMID 39090759, 2024). "To identify secreted cytokines/chemokines modulated by GLI1 in human cells, we used SSM2c melanoma cells, which express high levels of GLI1." (PMID 39090759, 2024). "In the attempt to elucidate the factors involved in this process, we identify CCL7 as one of the chemokines secreted by GLI1-silenced melanoma cells." (PMID 39090759, 2024). "Our data demonstrate the direct transcriptional regulation of CX3CL1 by GLI1 in melanoma cells, consistent with a recent study." (PMID 39090759, 2024). "We have previously demonstrated that CAXII is downregulated by SMO and GLI1 siRNA, resulting in melanoma migration and invasion impairment." (PMID 38399442, 2024). "Human monocyte-derived dendritic cells (moDCs) were cultured in CM from GLI1-silenced patient-derived melanoma cells to assess their activation and recruitment." (PMID 39090759, 2024). "This study has also shown that a decrease of GLI1 expression in a dose-dependent manner in an in vivo xenograft model for melanoma suggested the use of GLI1 as a mechanistic biomarker of response." (PMID 38342953, 2024). "RAS/RAF/ERK signaling promotes the proliferation and survival of melanoma cells by regulating the nuclear localization and transcriptional activity of the GLI1 transcription factor." (PMID 37239024, 2023).
melanoma (continued). "CREB3LI has been reported to be activated in drug-resistant cell lines and GLI1 knockout has been shown to increase sensitivity to vemurafenib, an approved melanoma BRAF inhibitor." (PMID 36894939, 2023). "The normal skin tissues showed few of these positive cells, and the number of SHH-, Gli1-, and Gli2-positive cells per mm2 was significantly higher in the melanoma tissues than in the normal skin tissues (p < 0.05)." (PMID 37240209, 2023). "Here, we analyzed surgically resected oral malignant melanoma specimens and observed that Sonic Hedgehog, Gli1, and Gli2 were highly expressed in tumor cells, vasculatures, and osteoclasts." (PMID 37240209, 2023). "For instance, RAS-RAF-MEK-ERK1/2 and AKT signaling can regulate the nuclear localization and transcriptional activity of GLI1 in normal fibroblasts and melanoma cells." (PMID 36674836, 2023). "Circ-Gli1 indirectly upregulated Cyr61 through the activation of the Hedgehog and Wnt pathways, thereby exacerbating melanoma metastasis and angiogenesis." (PMID 36517618, 2022). "Gli1 and Bcl-2 protein are highly expressed in melanoma A375 cells, and their expressions show a downward trend (P < 0.05) after being treated by cyclopamine." (PMID 35027924, 2022). "On the other hand, as ornidazole treatment also downregulated the expression of Gli1, it seems reasonable to argue that ornidazole activates the apoptosis through Gli1/Bcl2/Bax-axis in melanoma cells." (PMID 36325671, 2022). "The BRD4-SOX2-GLI1 transcriptional complex has also been seen in melanoma, where it acts to transactivate GLI-target genes such as GLI1 and ST3GAL1." (PMID 36556332, 2022). "In order to confirm HH-GLI pathway activation in melanoma cell lines, we analyzed relative gene and protein expression levels of the pathway components (GLI1, GLI2, GLI3, and PTCH1) on a panel of 14 human melanoma cell lines with different genetic backgrounds." (PMID 36139698, 2022). "In support of the biological relevance of the transcriptional regulation of GLI1 by SOX2, we found a statistically significant correlation between SOX2 and GLI1 expression in a panel of metastatic melanoma cells (Pearson score R = 0.664, p = 0.036)." (PMID 33958721, 2021). "Examination of melanoma patient specimens failing vemurafenib revealed that all were positive for GLI1 expression, while 40% were positive for GLI2 expression." (PMID 34572373, 2021). "Recently, a reciprocal regulation between SOX2 and GLI1 has been described to fuel aberrant glycosylation/sialylation during melanoma progression." (PMID 33958721, 2021). "In contrast, expression of Shh pathway components (Gli-1, Gli-2, and Ptch-1) in the nevi from P4 and P5 and melanoma markers (c-kit, MAGE, and CDK4) in the nevus from P1 was markedly increased." (PMID 33509032, 2021). "The existence of a positive regulation of ERK5 by the HH-GLI pathway was further investigated using melanoma cells that are characterized by a constitutive expression of GLI1." (PMID 34681917, 2021). "Silencing of BRD4 using two independent shRNAs (LV-shBRD4.1 and LV-shBRD4.2) strongly decreased the expression of GLI1 at both mRNA and protein level in melanoma cells." (PMID 33958721, 2021). "Since BRD4 is highly expressed in melanoma, we investigated its requirement in the binding and transactivation of GLI1 promoter by SOX2." (PMID 33958721, 2021). "Depletion of SOX2 using two independent shRNAs significantly decreased the expression of GLI1 mRNA and protein in several melanoma cell types." (PMID 33958721, 2021). "Consistently, authors demonstrated that ST3GAL1 mediates SOX2- and GLI1-induced melanoma invasiveness." (PMID 33921986, 2021). "In melanomas, the Hedgehog signaling is regulated by the interaction between GLI1 and RAS-MEK/AKT pathway." (PMID 34445421, 2021).
melanoma (continued). "Together, our data provide evidence of a novel mechanism of non-canonical activation of GLI1 by the SOX2-BRD4 transcriptional complex, and describe the efficacy of a new combinatorial treatment for a subset of melanomas with an active SOX2-BRD4-GLI1 axis." (PMID 33958721, 2021). "In the present study, we uncovered that hsa_circ_0027247, a novel circRNA annotated to GLI1 gene (called as circ-GLI1), was highly expressed in melanoma cells." (PMID 32732916, 2020). "Consistently, ectopic expression of ST3GAL1 in SOX2- or GLI1-depleted SSM2c cells was able to rescue the decrease in melanoma cell invasion produced by SOX2 or GLI1 silencing." (PMID 33203881, 2020). "In the last few years several studies have reported a role for the TGF-β-GLI1/2 axis, partially Smad3 dependent, in fibroblast activation, melanoma, stroke (ischemia/reperfusion injury), hepatocellular carcinoma, and gastric cancer." (PMID 32245491, 2020). "This is in agreement with previous studies showing that SOX2 and GLI1 are both involved in melanoma progression." (PMID 33203881, 2020). "Knock-down of GLI1 in the B16F10 mouse melanoma cell line resulted in a reduced invasive capacity in vitro and decreased lung metastasis ability in vivo." (PMID 32796736, 2020). "Circ-GLI1 was upregulated with highest fold change and had a potential to regulate Cyr61 in melanoma cells." (PMID 32732916, 2020). "We also testified that Cyr61 was the responsible mediator for circ-GLI1-contributed melanoma metastasis and angiogenesis both in vitro and in vivo." (PMID 32732916, 2020). "By and large, circ-GLI1 positively regulates Cyr61 in melanoma via its dual-activation on Hedgehog and Wnt/β-catenin pathways." (PMID 32732916, 2020). "Concordantly, Co-IP results illustrated that circ-GLI1 depletion strengthened the interaction of GSK3β with either GLI1 or β-catenin in melanoma cells." (PMID 32732916, 2020). "Of importance, it was proven that Cyr61 overexpression recovered the wound-healing ability which was abated in circ-GLI1-silenced melanoma cells." (PMID 32732916, 2020). "Thereafter, a novel circRNA hsa_circ_0027247 derived from GLI1 (circ-GLI1) was identified to positively modulate CYR61 expression in melanoma cell lines." (PMID 32732916, 2020). "More importantly, we observed that circ-GLI1 knockdown in melanoma cells pronouncedly retarded the formation of vascular branches, indicating that circ-GLI1 depletion hampered angiogenic process." (PMID 32732916, 2020). "In conclusion, circ-GLI1 exacerbates the metastasis and angiogenesis of melanoma by upregulating Cyr61 via p70S6K2-dependent activation of Hedgehog/GLI1 and Wnt/β-catenin pathways." (PMID 32732916, 2020). "Collectively, circ-GLI1 facilitates the protein levels of GLI1 and β-catenin in melanoma in a p70S6K2-mediated way." (PMID 32732916, 2020). "In sum, these findings proved that circ-GLI1 contributes to melanoma metastasis and angiogenesis via regulating Cyr61." (PMID 32732916, 2020). "Next to this, GLI family zinc finger 1 (GLI1) is proposed to be important for maintaining the invasive properties of melanoma cells in a ZEB2/MITF-independent manner but most likely ZEB1-dependent manner." (PMID 32796736, 2020). "Taken together, these findings unveiled that circ-GLI1 aggravates cell migration and angiogenesis in melanoma possibly through targeting Cyr61." (PMID 32732916, 2020). "Another study provided evidence that RAS/MEK and AKT signaling regulate the nuclear localization and transcriptional activity of GLI1 in melanoma and other cancer cells in response to SHh ligand." (PMID 33081032, 2020). "More importantly, we uncovered that circ-GLI1 modulated Cyr61 expression in melanoma cells through indirectly activating Cyr61 transcription." (PMID 32732916, 2020). "Activation of AKT signaling has been shown to enhance GLI1 nuclear localization and transcriptional activity in human melanoma cells, LNCaP prostate cancer cells and U87 glioma cells." (PMID 30934935, 2019).